TCN1 (transcobalamin 1)
Description:
Binds vitamin B12 with femtomolar affinity and protects it from the acidic environment of the stomach.
Synonyms: TC-1; HC; TCI; TC1
Tractability: Small molecule: a structure with a bound ligand is known. Antibody: its Gene Ontology location is reachable by antibodies, with high confidence; UniProt places it where antibodies can reach, with medium confidence; UniProt predicts a signal peptide or a membrane-spanning region. PROTAC: its protein half-life has been measured.
Gene: Protein-coding gene on chromosome 11 (59,852,800 to 59,866,489, reverse strand). Ensembl gene ENSG00000134827.
Subcellular location: Secreted
Pathways (Reactome):
Metabolism: Transport of RCbl within the body; Uptake of dietary cobalamins into enterocytes
Immune System: Neutrophil degranulation
Gene Ontology:
Molecular function: cargo receptor ligand activity; molecular sequestering activity; protein binding; cobalamin binding
Biological process: cobalamin transport
Cellular component: extracellular region; specific granule lumen; tertiary granule lumen
Genetic constraint (gnomAD): Loss-of-function variants: 50 observed, 51.57 expected, observed/expected ratio (o/e) 0.97, 90% interval 0.77 to 1.23. The upper end of that interval is the gene's LOEUF score, 1.23, which puts it in group 5 of 6, group 1 being the genes least tolerant of losing a copy. Missense variants: 532 observed, 538.94 expected, observed/expected ratio (o/e) 0.99, 90% interval 0.92 to 1.06. Synonymous variants: 183 observed, 203.26 expected, observed/expected ratio (o/e) 0.9, 90% interval 0.8 to 1.02.
Homologues: Orthologues: chimpanzee TCN1 (99% identical), macaque TCN1 (87% identical), rabbit TCN1 (69% identical), dog TCN1 (63% identical), pig TCN1 (58% identical), Drosophila melanogaster CG3556 (19% identical). Paralogues in human: CBLIF (30% identical), TCN2 (28% identical).
Diseases named in the same sentence as TCN1 in open-access papers:
TCN1 is named in the same sentence as 61 diseases in open-access papers, as found by Europe PMC text mining. Sharing a sentence is not in itself a finding about the gene and the disease. The quoted sentences say what the papers report.
colon cancer (11 papers, 2020 to 2025). "TCN1 has been reported to be part of neutrophil secondary granules and has been associated as a poor prognostic biomarker in colon cancer." (PMID 39676870, 2024). "This provided further evidence that TCN1 expression was associated with colon cancer behaviour and prognosis." (PMID 32686693, 2020). "All the studies revealed that TCN1 expression in colon cancer was significantly associated with malignant biological behaviour." (PMID 32686693, 2020). "Upregulation of TCN1 has been reported in the cytoplasm of tumor tissues, and TCN1 is overexpressed in some malignant tumors and associated with tumor proliferation and metastasis, such as colon cancer, hypopharyngeal squamous cell cancer, breast cancer, and gastric cancers." (PMID 35287670, 2022). "A total of 194 cases of colon cancer were examined by immunohistochemistry and revealed that TCN1 expression level was related to advanced stages (P < 0.005)." (PMID 32686693, 2020). "TCN1 expression was significantly higher in colon cancer tissues than in adjacent normal tissues (73.20% vs. 5.67%, P < 0.01)." (PMID 32686693, 2020). "Western blotting (n = 9) and quantitative real time polymerase chain reaction (qRT-PCR, n = 30) revealed that TCN1 was highly expressed in colon cancer tissues at both the protein and mRNA level." (PMID 32686693, 2020). "IHC in TMAs proved that TCN1 was highly expressed in colon cancer tissues and demonstrated that high expression levels were correlated with advanced pathological features." (PMID 32686693, 2020). "We also found that the expression of TCN1 was higher in right-sided colon cancer than in left-sided." (PMID 32686693, 2020). "Next-generation sequencing showed that TCN1 was one of several upregulated mRNAs in colon cancer, which was verified by further bioinformatics analyses." (PMID 32686693, 2020). "Western blot and qRT-PCR assays revealed that TCN1 was highly expressed in most of colon cancer tissues both at the protein and mRNA level, but was poorly expressed in adjacent normal colon mucosal tissues." (PMID 32686693, 2020). "Taken together, we conclude that TCN1 expression is significantly overexpressed in colon cancer and is correlated with advanced pathological features." (PMID 32686693, 2020). "IHC staining of tissue microarray (TMA) slices also verified that TCN1 was highly expressed in colon cancer tissues (73.20%, 142/194) and pulmonary metastatic tumours (83.78%, 31/37)." (PMID 32686693, 2020). "NGS, western blotting, and immunohistochemistry (IHC) revealed that TCN1 was highly expressed in colon cancer tissues compared with adjacent normal mucosal tissues at both the protein and mRNA level." (PMID 32686693, 2020). "Pulmonary metastatic tumour tissue from colon cancer also showed high expression of TCN1 and the expression level was in accordance with that in the primary colon cancer tissues." (PMID 32686693, 2020). "The present study aimed to detect TCN1 as a novel biomarker for prognosis and chemosensitivity of colon cancer." (PMID 32686693, 2020). "TCN1 acts as a biomarker for the prognosis of various cancers, including colon cancer, gastric cancer, and LUAD, and it could promote the migration and invasion of cancer cells." (PMID 36793937, 2023). "Additionally, bioinformatics analyses have confirmed that the mRNA expression of TCN1 was upregulated in common colon cancer; both Yang’s study and our model identified this gene." (PMID 36685928, 2022). "For example, RPRM is a gastric cancer biomarker, and TCN1 high expression was linked to negative colon cancer prognosis." (PMID 34804955, 2021). "Thus, we can conclude that high expression of TCN1 is significantly correlated with advanced clinicopathological features and poor prognosis of colon cancer." (PMID 32686693, 2020). "In addition, TCN1 was highly expressed in pulmonary metastatic tumour tissues (n = 37, P = 0.025) and exhibited higher levels in right-sided colon cancer than in left-sided colon cancer (P = 0.029)." (PMID 32686693, 2020).
colon cancer (continued). "Therefore, TCN1 could be used as a novel biomarker for colon cancer aggressiveness and prognosis and might also be a potential biomarker for predicting neoadjuvant chemosensitivity." (PMID 32686693, 2020). "We hypothesized that TCN1 might have a role in colon cancer." (PMID 32686693, 2020). "Thus, it could be inferred that TCN1 performed roles in colon cancer progression and metastasis." (PMID 32686693, 2020). "TCN1 also has important roles in cell proliferation and has been shown to be highly expressed by colon cancer cells and proposed as a negative prognostic biomarker." (PMID 40076885, 2025). "Furthermore, positive TCN1 expression was significantly correlated with T, N, M, TNM stage and age and was higher in right-sided colon tumors than in left-sided tumors." (PMID 32686693, 2020). "Previous research had shown that a high expression of TCN1 was a negative prognostic factor in colon cancer and might correlate with the patients’ chemosensitivity." (PMID 36059555, 2022).
gastric cancer (7 papers, 2011 to 2023). A primary or metastatic malignant neoplasm involving the stomach. "The rs526934 variant in TCN1 gene was found to be associated with lower circulating vitamin B12 concentrations and an increased risk of developing gastric cancer." (PMID 36275653, 2022). "In gastric cancer studies, TCN1 was significantly correlated with cancer stage, poor cell differentiation, lymph node metastasis, and a poor prognosis." (PMID 24959000, 2014). "Also, there was a better correlation between TCN1 and progression of gastric cancer than vitamin B12." (PMID 35287670, 2022). "Of these 12 genes, 7 genes highly expressed in gastric cancer tissues were down-regulated (ITGB5, TYMS, MYB, APOC1, CBX5, PLA2G2A, KIF20A) and 5 low-expressed genes were up-regulated after vorinostat treatment (SCGB2A1, TCN1, CFD, APLP1, NQO1." (PMID 21931799, 2011).
colorectal cancer (5 papers, 2014 to 2025). A primary or metastatic malignant neoplasm that affects the colon or rectum. "High TCN1 expression is associated with chemotherapy resistance in colorectal cancer." (PMID 35631199, 2022). "The TCN1 intronic SNP rs526934 was associated with gastric cancer risk (OR 2.09 [95% CI: 1.25–3.51]) and the risk of colorectal cancer was increased in homozygote subjects with the TCN2 c.776C>G (OR 2.9 [95% CI: 1.1–7.6]) and the c.1026-394T>G (OR 3.1 [95% CI: 1.2–8.2]) variant alleles." (PMID 35631199, 2022). "Consistent with the oncogenic roles of TCN1 in colorectal cancer, cholangiocarcinoma, and other gastrointestinal malignancies, we observed significant upregulation of TCN1 in PDAC tissues." (PMID 41154358, 2025). "TCN1 may play a carcinogenic role in colorectal cancer by regulating the ITGB4 signaling pathway leading to cytoskeleton damage and promoting cell death." (PMID 38035071, 2023). "In colorectal cancer (CRC), Transcobalamin 1 (TCN1) disrupts the cytoskeletal network through modulation of ITGB4 signaling." (PMID 39169946, 2024).
lung cancer (5 papers, 2022 to 2023). A malignant neoplasm involving the lung. "TCN1 has been suggested as a potential marker for granulocyte differentiation and an unfavorable prognostic marker in renal and lung cancers." (PMID 36364737, 2022). "The correlation of the four genes HMMR, PFKP, TCN1, and TK1 with tumor-infiltrating immune cells and the survival curve in lung cancer was shown." (PMID 35898471, 2022). "In cells with high levels of endogenous TCN1 expression, including gastric epithelial and human nonsmall cell lung cancer cell lines (GES1 and HCC827), we found that TCN1 overexpression or VB12 supplementation did not promote cell proliferation." (PMID 35716043, 2023).
breast carcinoma (4 papers, 2016 to 2025). "GEPIA results indicate that higher expression of the 1CM-participating gene TCN1, measured in TPM, is associated with a higher overall survival rate in patients with breast cancer (plogRank = 0.0007)." (PMID 39125744, 2024). "Furthermore, survival enrichment analyses between the 1CM-related genes and survival in breast cancer indicate that a higher expression of TCN1 correlates with a higher overall survival." (PMID 39125744, 2024).
COVID-19 (4 papers, 2020 to 2025). A disease caused by infection with severe acute respiratory syndrome coronavirus 2. "In infectious diseases such as COVID-19, TCN1 has been linked to poor outcomes, with vitamin B12 deficiency associated with a worse prognosis." (PMID 41221285, 2025). "Furthermore, the genes ELANE, AZU1, MPO, PRTN3, CTSG, and TCN1 were shown to be significantly altered in patients with COVID-19, and our automatically prepared knowledge base highlights all of them as associated with COVID-19 with “medium” or “low” confidence." (PMID 33055059, 2020).
lung adenocarcinoma (4 papers, 2022 to 2025). A carcinoma that arises from the lung and is characterized by the presence of malignant glandular epithelial cells. "TCN1 is closely related to the molecular targets of lung adenocarcinoma BRAF, HHLA2, and CD274 (PD-L1), especially BRAF and HHLA2." (PMID 35287670, 2022). "These may be the potential mechanisms of TCN1 leading to poor prognosis of lung adenocarcinoma." (PMID 35287670, 2022). "TCN1 also had a good ability to distinguish lung adenocarcinoma from non-lung adenocarcinoma samples [area under the curve (AUC) = 0.788]." (PMID 35287670, 2022).
rectal cancer (4 papers, 2020 to 2024). A primary or metastatic malignant neoplasm that affects the rectum. "Many studies have focused on identifying genes as biomarkers associated with tumor response and survival prognosis of rectal cancer patients with pCRT, such as SERPINB5, CHD4, TCN1, VNN1, EPHA4, PCSK1, and DUOX2 genes." (PMID 33506057, 2021). "As a vitamin B12 binding protein, TCN1 has been suggested to be an unfavorable prognostic factor among rectal cancer patients undergoing CCRT in our previous study." (PMID 34357018, 2021). "TCN1 was associated with breast phyllodes tumors and was noticed to be a negative indicator in prognostic evaluation of rectal cancer." (PMID 35073659, 2024). "Currently, a lot of previous studies have reported that genes SERPINB5, CHD4, TCN1, VNN1, EPHA4, PCSK1, and DUOX2 as prognostic biomarkers were proven to correlate with poor tumor response and survival prognosis in patients with rectal cancer receiving pCRT." (PMID 33506057, 2021).
hepatocellular carcinoma (3 papers, 2012 to 2022). A malignant tumor that arises from hepatocytes. "It was reported that high levels of TCN1 in human serum are associated with leukemia, hepatocellular carcinoma, and phyllodes of breast tumors." (PMID 35719915, 2022). "The expression of TCN1 was also reported to be increased in hepatocellular carcinoma and immunodeficiency virus (HIV) seropositive patients." (PMID 35287670, 2022).
metastatic tumors (3 papers, 2017 to 2025). "SLC6A14 (solute carrier family 6, member 14) and TCN1 (transcobalamin 1) were down-regulated genes in primary and metastatic tumors." (PMID 28086829, 2017).
psoriasis (3 papers, 2012 to 2022). An autoimmune condition characterized by red, well-delineated plaques with silvery scales that are usually on the extensor surfaces and scalp. "The impact of the classifier genes can be studied alone, such as for TCN1, or they can be considered together as the molecular definition of psoriasis, which could aid in differential diagnosis." (PMID 22957057, 2012). "Namely, RHCG, TCN1, KLK6, and LCN2 were chosen for psoriasis and CCL17, NCF4, BATF3, and CLEC4G as ACD-specific genes." (PMID 25058585, 2014).
Sepsis (3 papers, 2021 to 2025). Sepsis is defined as life-threatening organ dysfunction caused by a dysregulated host response to infection. "Altered TCN1 levels have also been observed in sepsis, likely due to its role in immune modulation and cellular metabolism." (PMID 41221285, 2025). "Artificial intelligence systems identified eight out of twenty novel genetic markers (SDC4, CLEC5A, TCN1, MS4A3, HCAR3, OLAH, PLCB1, and NLRP1) that help predict sepsis severity or mortality." (PMID 33692779, 2021).
asthma (2 papers, 2025). "We identified 8 key genes (LOC100132287, CEACAM5, PRR4, CPA3, POSTN, LYPD2, TCN1, and SCGB3A1) associated with asthma by combining the LASSO regression model and the SVM-RFE method." (PMID 39963184, 2025). "In our study, TCN1 showed excellent discrimination ability, which indicated that TCN1 was expected to be a candidate biomarker for asthma and UC." (PMID 40443529, 2025). "In conclusion, our bioinformatics analysis identified NOS2, TCN1, CHI3L1 and TIMP1 as potential diagnostic biomarkers for asthma and UC." (PMID 40443529, 2025). "The association of the five genes CEACAM5, POSTN, TCN1, SCGB3A1, and CPA3 with asthma has been extensively identified and validated, and these are the most highly upregulated genes in patients with asthma, and CEACAM5 is associated with resting mast cells and eosinophils." (PMID 39963184, 2025). "In addition, we identified NOS2, TCN1, CHI3L1, and TIMP1 as possible diagnostic markers for UC and asthma." (PMID 40443529, 2025). "GSEA analysis showed that NOS2, TCN1, CHI3L1 and TIMP1 were jointly involved in cytokine receptor interaction in asthma and ulcerative colitis chemokine signaling pathway." (PMID 40443529, 2025). "In conclusion, NOS2, TCN1, CHI3L1 and TIMP1, as key immune and inflammatory regulatory targets, play an important role in the comorbidity of asthma and ulcerative colitis." (PMID 40443529, 2025). "PRR4, TCN1, CST1, CLCA1, and NOS2 were also highly expressed in patients with asthma in GSE158752 dataset." (PMID 39963184, 2025). "Then, the genes selected by the two methods were crossed, and finally, the key genes involved in the progression of asthma to UC (CXCL13, NOS2, TCN1, CHI3L1 and TIMP1) were obtained." (PMID 40443529, 2025). "We further used a one-to-one format for comparison and validated with the GSE63142 dataset The genes CEACAM5, PRR4, CPA3, POSTN, TCN1, CST1 (Cystatin-SN), CLCA1, TPSAB1 and NOS2 (Nitric oxide synthase 2) were highly expressed in patients with asthma." (PMID 39963184, 2025). "This study highlights NOS2, TCN1, CHI3L1, and TIMP1 as potential biomarkers and therapeutic targets for asthma and UC, providing insights into shared mechanisms and new strategies for diagnosis and treatment." (PMID 40443529, 2025). "The results showed that only four genes (NOS2, TCN1, CHI3L1, TIMP1) showed statistically significant differences in expression in the data sets validated by asthma and UC compared with the control group." (PMID 40443529, 2025).
cobalamin deficiency (2 papers, 2018 to 2025). "This inverse correlation is consistent with the fact that TCN1 is able to bind circulating vitamin B12 but unable to mediate cellular uptake, and with the well-known effect of vitamin B12 deficiency on memory performance." (PMID 30139959, 2018).
influenza (2 papers, 2021 to 2023). An acute viral infection of the respiratory tract, occurring in isolated cases, in epidemics, or in pandemics; it is caused by serologically different strains of viruses (influenzaviruses) designated A, B, and C, has a 3-day incubation period, and usually lasts for 3 to 10 days. "As of yet, the mechanisms to explain decreased protein levels of TCN1 in severe influenza infection are unknown, and the phenomenon and causes deserve further investigation." (PMID 33448094, 2021). "For example, TCN1, as a VitB12 binding protein, may be more related to gastrointestinal illness than just severe influenza infection." (PMID 33448094, 2021).
memory impairment (2 papers, 2014 to 2018). "The relationship between TCN1 expression and memory impairment was comparable to that of important determinants of memory function such as age and sex, suggesting that TCN1 could be a clinically relevant marker of memory performance." (PMID 30139959, 2018).
Obesity (2 papers, 2022 to 2025). Accumulation of substantial excess body fat. "We only found five genes shared between both groups (MUCL3, PGC, TCN1, TFF2, BPIFB1) that were upregulated in MO-low-IR but downregulated in MO-high-IR when compared with women without obesity." (PMID 35625760, 2022).